HDX (highly divergent homeobox)
Synonyms: CXorf43; FLJ30678; D030011N01Rik
Tractability: PROTAC: UniProt records ubiquitination sites on it.
Gene: Protein-coding gene on chromosome X (84,317,874 to 84,502,496, reverse strand). Ensembl gene ENSG00000165259.
Subcellular location: Nucleus
Subcellular location (Human Protein Atlas): Cytosol
Gene Ontology:
Molecular function: protein binding; DNA-binding transcription factor activity, RNA polymerase II-specific; RNA polymerase II cis-regulatory region sequence-specific DNA binding; DNA binding
Biological process: regulation of transcription by RNA polymerase II
Cellular component: chromatin; RNA polymerase II transcription regulator complex; nucleus
Homologues: Orthologues: chimpanzee HDX (99% identical), macaque HDX (98% identical), rabbit HDX (94% identical), rat Hdx (91% identical), mouse Hdx (91% identical), pig HDX (89% identical), guinea pig HDX (88% identical), tropical clawed frog hdx (56% identical), zebrafish hdx (34% identical), Drosophila melanogaster acj6 (7% identical), Caenorhabditis elegans unc-86 (6% identical). Paralogues in human: POU2F1 (13% identical), POU6F2 (11% identical), POU2F2 (10% identical), POU2F3 (10% identical), POU6F1 (10% identical), POU3F3 (10% identical), POU3F4 (9% identical), POU3F2 (9% identical), POU4F3 (9% identical), POU3F1 (8% identical), POU5F1 (8% identical), POU4F2 (8% identical), and 5 more.
Diseases named in the same sentence as HDX in open-access papers:
HDX is named in the same sentence as 6 diseases in open-access papers, as found by Europe PMC text mining. Sharing a sentence is not in itself a finding about the gene and the disease. The quoted sentences say what the papers report.
premature ovarian failure (1 paper, 2019). "Disruption of HDX, encoding a highly divergent homeobox protein with DNA-binding activity, and POF1B, encoding an actin-binding protein, have both been associated with premature ovarian failure." (PMID 31514470, 2019).
tumor (1 paper, 2020). "This rise was not due to conversion of HDX (Xanthine dehydrogenase) to XO, since the HDX activity was significantly lower in tumor versus healthy tissue." (PMID 32899343, 2020).
HDX also shares sentences with these, for which no sentence is quoted: breast carcinoma (1 paper); cancer (1); neuroblastoma (1); thyroid cancer (1).